CDK2 (cyclin dependent kinase 2)
Diseases named in the same sentence as CDK2 in open-access papers (continued):
Sharing a sentence is not in itself a finding about the gene and the disease.
cancer (continued). "Cyclin A2/CDK-2, promotes cancer progression by driving the cell-cycle transition from S phase to G2 phase." (PMID 38801618, 2024). "Among the investigated derivatives, St.8 showed the best activities against various cancer cell lines besides potent activities on CDK2, as well as this compound, which arrests the cell cycle at S and G2/M phases and induces apoptosis." (PMID 39404419, 2024). "Another key player in cancer pathogenesis is CDK2, which is a serine/threonine protein kinase that plays a role in the G1/S transition, the initiation of DNA synthesis, and the regulation of the exit from the S phase." (PMID 38611505, 2024). "In cancer, the dysregulation of CDK2 is often observed, contributing to the unchecked growth of cancer cells." (PMID 38474160, 2024). "Our findings strengthen the notion that CDK2 is a relevant and promising target for cancer therapy and support the current efforts by Incyclix Bio, Pfizer, Blueprint Medicines, Incyte, and Allorion Therapeutics to develop CDK2 inhibitors in the clinic." (PMID 38047585, 2024). "A reduction in the phosphorylation levels of CDK1/2/3 and Rb was observed in sh-DNMT1 cancer cells compared to sh-NC cells, confirming the additional inhibition of CDK2-Rb signal transduction." (PMID 38755637, 2024). "By targeting CDK2, it is possible to halt the proliferation of cancer cells, inducing cell cycle arrest, potentially leading to cancer cell death." (PMID 38474160, 2024). "The structures and the IC50 values against a panel of cancer cell lines and CDK2 for the most active agents which contain Thiazole, and Thiouracil scaffolds." (PMID 39404419, 2024). "Erik’s report illustrate the complex nature of cancer cell cycles, genes (CDK4, CDK6, CCND1, CDK2, and CCNE1) that regulate the G1/S transition yield particularly variant vulnerabilities in different cancer cell." (PMID 38582921, 2024). "In parallel, through this line of evidence, Cyclin E, encoded by CCNE1, is an established cell cycle protein, forming a complex with Cdk2 and promoting the shift from the G1 to S phase of the cell cycle, a function required for cancer malignancy." (PMID 38275417, 2024). "The aim of this study was to develop a novel CDK2 inhibitor to provide a new therapeutic option for cancer patients with CCNE1 overexpression and resistance to CDK4/6 inhibitors." (PMID 38338471, 2024). "Ebvaciclib, the first targeted therapeutic drug to undergo clinical trials for cancer patients, is a highly effective and orally accessible small-molecule inhibitor of CDK2/4/6." (PMID 38998978, 2024). "The efficacy of this agent in preclinical models of both CCNE1-amplified and CDK4/6i–resistant cancers was encouraging and supported the rationale for targeting CDK2 in cancer, but its clinical development has been discontinued." (PMID 38047585, 2024). "CDK2 in tumors plays a pivotal role in cell cycle regulation and proliferation control, potentially serving as a promising therapeutic target for cancer treatment." (PMID 38305770, 2024). "CDK2 is a crucial protein in cancer biology, primarily involved in the regulation of the cell cycle." (PMID 38474160, 2024). "Recognizing CDK2’s multifaceted role in cancer development, researchers have focused on its inhibition as a therapeutic strategy." (PMID 38398626, 2024). "CDK-2 is highly expressed in various tumor cells and is considered to play an important role in the formation and development of malignant tumors." (PMID 39057425, 2024). "CDK2 plays a critical role in cancer progression by regulating the cell cycle and phosphorylating retinoblastoma protein (Rb), particularly during the G1–S phase transition." (PMID 38755637, 2024). "Ebvaciclib, developed by Pfizer Inc., not only demonstrates potent pharmacological activity and inhibits tumor growth in multiple cancer models by targeting CDK2/4/6, but it also has the potential to enhance the anti-tumor immune response." (PMID 38998978, 2024).
cancer (continued). "Other highly potent CDK-2-selective inhibitors that are undergoing phase I trial investigation in cancers include PF-07104091 and BLU-222." (PMID 38732271, 2024). "These literature data are consistent with the observed growth arrest in the Ca9-22 cancer cell populations in the G2 or M phase by W-R EtOAc (125 μM) and W-R BuOH (250 μM) and highlight the involvement of CDK2 inhibition of as a molecular anticancer mechanism." (PMID 38303989, 2024). "CDK2, known for its crucial involvement in the cell cycle process, has emerged as a promising therapeutic target for treating cancer." (PMID 38755637, 2024). "The structures and the IC50 values against a panel of cancer cell lines and CDK2 for the most active agents, which contain pyrazole, pyrimidine, and pyridine scaffolds." (PMID 39404419, 2024). "In cancer cells, the CDK2–cyclin E complex regulates DNA replication, while the cyclin A–CDK2 complex plays a pivotal role during the S phase and contributes to triggering of the G2/M transition." (PMID 38474202, 2024). "The anticancer potential of the major chemical compound (3-Isobutylhexahydropyrrolo[1,2-a]pyrazine-1,4-dione) was first demonstrated by molecular docking analysis with the CDK2 protein and cytotoxicity assays against three cancer cell lines." (PMID 39597689, 2024). "In these cancers, CCNE1 amplification is associated with high levels of cyclin E1 protein, CDK2-dependent proliferation, chemotherapy resistance, and a poor prognosis." (PMID 38047585, 2024). "In cancer, curcumin’s effectiveness is determined by examining its interaction with pivotal proteins like CDK2, CK2α, GSK3β, DYRK2, and EGFR, among others." (PMID 38474160, 2024). "In the current study, molecular hybridization between the oxindole core and benzothiazole system through an acetohydrazide moiety was accomplished for the design of a new series of oxindole–benzothiazole hybrids 9a–r targeting CDK2 for cancer therapy." (PMID 39272187, 2024). "CDK2 is altered in 0.16% of all cancers, yet specifically colon adenocarcinoma possesses the greatest prevalence of alterations." (PMID 38611505, 2024). "Several studies reported the up-regulation of CDK2 in diverse types of cancer including breast cancer, prostate cancer, liver cancer and lung cancer." (PMID 39272187, 2024). "Abnormal expression of cyclins, the regulatory subunits essential for CDK2 activity, further underscores its oncogenic potential, particularly through overexpression of cyclin A and/or E in various cancers." (PMID 38398626, 2024). "Pharmacophore-based inverse virtual screening proposed that BRD3 and CDK2 are the cancer-relevant targets for the annotated withanolides D and O, and the flavonoid kaempferol." (PMID 38303989, 2024). "Previous research revealed that cyclin-dependent kinase-2 (CDK2) is a valid anti-cancer target for pyran-containing compounds." (PMID 38707385, 2024). "Analysis of the lead chemical compound with the cancer therapeutic target CDK2 using docking simulation has also yielded positive results." (PMID 39597689, 2024). "These experiences, coupled with a knowledge of a specific role for CDK2 in driving growth of certain cancers, has driven efforts to develop compounds that selectively inhibit CDK2." (PMID 38047585, 2024). "This study aims to explore the mechanism of the binding of CDK2/4/6 kinases and their inhibitors to design novel CDK2/4/6 inhibitors for significantly enhancing their potency in different kinds of cancers." (PMID 38856753, 2024). "Like CDKs 4 and 6, there are cogent arguments supporting the development of selective CDK2 inhibitors for certain cancers." (PMID 38047585, 2024). "Glabridin inhibits cancer cell proliferation and survival by downregulating cyclin D3, CDK2, and CDK4, blocking the G1/S phase transition, and reducing CREB and ATF1 phosphorylation." (PMID 39723390, 2024). "CDK2 expression is upregulated in cancers, and CDK2 is crucial for anchorage-independent proliferation mediated by oncogenes." (PMID 37742010, 2023).
cancer (continued). "CircFOXO3 binds to CDK2 and p21, contributing to the formation of the circFOXO3-p21–CDK2 ternary complex and then serving as a scaffold, affecting cancer cell-cycle progression." (PMID 36902000, 2023). "IMMT levels positively correlated with biomarkers linked to cancer proliferation (KI67, PCNA, and MCM2) and with key regulators of the cell cycle (CDK4, CDK2 and CDK1)." (PMID 36899366, 2023). "In the past few decades, CDK2 has been regarded as a therapeutic boulevard to restrain cancer cell proliferation, more importantly, many small-molecule inhibitors with various scaffolds have been developted." (PMID 36342274, 2023). "Overall, the data indicate that the top 5 CDKs, CDK1 (11/32 or 34.4%), CDK2 (10 /32 or 31.3%), CDK6 (8/32 or 25%), CDK7 (9/32 or 28.1%), and CDK19 (8/32 or 25%), are closely associated with survival probability in various cancers." (PMID 37311884, 2023). "Cancer therapy is thought to target CDK2 in some cases, and several small-molecule CDK2 inhibitors are currently undergoing clinical trials." (PMID 37742010, 2023). "This approach aims to provide the rationale for the therapeutic potential of CDK2-specific cancer treatment and the development of new-generation cancer therapeutics." (PMID 37626747, 2023). "Cancer cell lines that are sensitive to the CHK1 inhibitor MK‐8776 from multiple cancer entities have also shown rapid accumulation of CDK2‐activated DNA double‐stranded breaks." (PMID 36373784, 2023). "In a similar manner, I3C has been shown to inhibit cancer progression in lung tumors by downregulating levels of cyclin E and its partner CDK2, enhancing apoptotic cell death." (PMID 37509102, 2023). "Some of these genes, such as MAPK, NOS2, CDK2, and TIMELESS, have been previously associated with VIP in non-cancer models." (PMID 37444395, 2023). "In turn, it was shown that the under-expression of LATS2 induced a high expression of CDK2, promoting the transition of cancer cells from the G1 to the S phase of the cell cycle." (PMID 37761387, 2023). "CDK2/9 antagonism with CYC065 (Fadraciclib)-treatment disordered centrosome stoichiometry in aneuploid cancer cells, preventing centrosome clustering." (PMID 38031910, 2023). "Cyclin-dependent kinase 2 (CDK2) is a promising target for cancer treatment, developing new effective CDK2 inhibitors is of great significance in anticancer therapy." (PMID 37626747, 2023). "For example, the levels of p21waf1/Cip1 and Chk1 were enhanced, while the levels of p35, Cyclin-Dependent Kinase 2 (CDK2) and cyclin B1 were decreased in cancer cells." (PMID 37239974, 2023). "CDK2 knock-down statistically significantly increased the presence of chromosome rings and multipolar mitoses in the studied cancer cells." (PMID 38031910, 2023). "Cyclin-dependent kinase 2 (CDK2) is a DNA damage signaling kinase, which phosphorylates proteins in many cellular processes and is hyperactivated in most cancers." (PMID 37869102, 2023). "Cyclin-dependent kinase 2 (CDK2) has been garnering considerable interest as a target to develop new cancer treatments and to ameliorate resistance to CDK4/6 inhibitors." (PMID 37049714, 2023). "Dinaciclib is still in clinical trials and considered as a research drug against such cancers targeting CDK2." (PMID 37925393, 2023). "The results showed that the combined treatment inhibited the expression of cyclin-dependent kinase 2 (CDK2) at the mRNA level (p < 0.05) in both pan-cancer cell lines." (PMID 37958642, 2023).
cancer (continued). "CDK4/6 and CDK2 are the dominant CDKs that control cell G1/S transition though finely tuned regulation of the phosphorylation of the Rb cancer suppressor, which subsequently releases E2F, a transcriptional factor involved in cell cycle regulation." (PMID 37563111, 2023). "Overall, the activity of both CDK2 and the regulatory subunits is involved in the onset of the oncogenic process in human cancers." (PMID 37626747, 2023). "Unsurprisingly, the aberrant activation of CDK2, which occurs in many human cancers, leads to uncontrolled cell proliferation during oncogenesis." (PMID 35595767, 2022). "Cyclin-dependent kinase 2 (CDK2) belongs to the serine/threonine protein kinase family, and the CDK2 activity is found to be typically high in different types of human cancers." (PMID 35801486, 2022). "Taken altogether, we proposed a putative model in which HHT blocks the interaction between CDK2 and Cyclin A. This enhances interactions between CDK2 and Trim21, which recruits autophagic machinery to degrade CDK2 in cancer cells." (PMID 35595767, 2022). "Cyclin-dependent kinase 2 (CDK2) is also a key mediator of cell cycle progression and plays a crucial role in the migration and metastasis of cancer cells." (PMID 35865946, 2022). "Both Cdk2 and Hsp90 are candidates for cancer therapy, and some clinical trials are currently in progress using Cdk2 or Hsp90 inhibitors." (PMID 35039060, 2022). "Inhibiting Cyclin-dependent kinase 2 (CDK2) has been established as a therapeutic strategy for the treatment of many cancers." (PMID 35139719, 2022). "The findings of CDK2-mediated PXR degradation indicate a wide range of potential drug–drug interactions during clinical cancer therapy using CDK inhibitors and imply an alternative direction for the development of novel PXR antagonists." (PMID 35053380, 2022). "While it makes CDK2 an attractive target for cancer therapy, most inhibitors against CDK2 are ATP competitors that are either nonspecific or highly toxic, and typically fail clinical trials." (PMID 35595767, 2022). "The mechanistic study based on the transcriptomic data revealed that erdafitinib exerted its anti-cancer effect by affecting the cell cycle-related pathway, and CDK2 was the regulatory target of this drug." (PMID 36235266, 2022). "Significantly, the enhanced inhibitory profile of PHA-767491 is mediated by potent inhibition of both DDK and the CDK2-Rb-E2F transcriptional network, that provides the molecular basis for its increased anti-proliferative effects in RB+ cancer cell lines." (PMID 36009559, 2022). "CircFoxo3 induced cell cycle arrest and suppressed cancer cell proliferation by combining with cell cycle-related proteins, cyclin-dependent kinase 2 (CDK2), and cyclin-dependent kinase inhibitor 1 (p21)." (PMID 35656022, 2022). "CDK2 also was a biomarker for other cancers and next-generation CDK2 inhibitors play an increasingly pivotal role in the treatment of cancer." (PMID 36601052, 2022). "This showed that CDK1 can substitute for CDK2 in triggering the S-phase, while, in cancer cells, CDK2–cyclin B complexes allow for the onset of mitosis in the absence of CDK1." (PMID 35805103, 2022). "Cell cycle delays caused by disorders in levels of cyclin E, Cdk2 and EF2F expression are often associated with the progression of various human cancers." (PMID 36547888, 2022). "We testedthis method using a well-studied cancer drug target,CDK2, using two drug molecules with measured kinetic profiles." (PMID 35195418, 2022). "Increasing evidence suggests that CDK2 fundamentally functions in the cell cycle, DNA replication, and DNA damage of particular cancer types." (PMID 36325324, 2022). "Although CDK2 is an attractive target to treat cancer, its utility within a clinical setting has been impeded by two major hurdles." (PMID 35595767, 2022). "When CDK2 inhibitors are applied to a range of cancer cells in vitro and tumor mice models in vivo, the inhibitors exhibit an encouragingly anti-tumor effect." (PMID 35595767, 2022).
cancer (continued). "The in vivo study showed that erdafitinib presented an obvious anti-cancer effect in the A549 xenograft mice model, which was accompanied by the reduced expression of CDK2." (PMID 36235266, 2022). "Anti‐Chi3L1 antibody significantly decreased the expression of cancer growth and migration‐associated proteins, such as PCNA, cyclin D1, cyclin E, Cdk2, Cdk4, Cdk5, MMP2 and MMP9 in A549 lung metastasis model tissues." (PMID 34861103, 2022). "During cell cycle progression, cyclin D1 and CDK2 are critical cell cycle regulators involved in the G0/G1 to S phase transition and serve as theraputic targets in several types of cancers, including NSCLC." (PMID 35235599, 2022). "miR-200c controlled cell cycle progression and cell growth by down-regulating the G1-S regulator CDK2, and had anti-cancer impacts in ccRCC." (PMID 35154284, 2022). "Targeting Cdk2 shows promising prospects for human cancers, especially in c-Myc-overexpressing cancers." (PMID 35039060, 2022). "Roscovitine is one of the members of the CDK-inhibitor family, primarily inhibiting CDK2 to restrict the proliferation of cancer cells." (PMID 36551263, 2022). "DHA and EPA triggered cell cycle arrest at the G0/G1 phase, which was accompanied by a reduction in the protein levels of CDK2 and cyclin E in human cancer cells." (PMID 36547898, 2022). "Suppression of active Ras and active MAPK, block of cyclin A gene expression and suppression of CDK2-cyclin A activity are events which while specific to the control of a cell cycle phase in normal cells are part of the apoptotic network in cancer cells." (PMID 34737438, 2022). "Previous studies have demonstrated that Ganoderma polysaccharides can prevent cancer growth by affecting the expression of cell cycle-related genes p21 and CDK2." (PMID 35865946, 2022). "Here, we revealed that SLCO4A1-AS1 exerts tumour-promoting functions by regulating the Cdk2-c-Myc axis in CRC, suggesting that targeting SLCO4A1-AS1 appears to be an alternative strategy for inhibiting the Cdk2-c-Myc axis in cancer therapy." (PMID 35039060, 2022). "Given CDK2's druggable nature and frequently dysregulated expression in a variety of cancers, additional research is likely to be crucial for the development of CDK2 inhibitors as anticancer drugs." (PMID 36065423, 2022). "We found less literature on anthraquinone analogue binding mechanisms and interaction energy with caspase-3, apoptosis regulator Bcl-2, TNIK, and CDK2, important cancer-related protein targets." (PMID 36355520, 2022). "On the other hand, overexpression of cyclin-dependent kinase 2 (CDK-2) is a major factor causing abnormal regulation of the cell cycle, which is directly associated with excessive proliferation in cancer cells." (PMID 36505739, 2022). "In this regard, the conjugated compounds XVI, XVII, and XVIII are examples of s-triazine analogs that have shown significant inhibitory activity against CDK-2 and therefore significant activity against a wide spectrum of cancer cell lines." (PMID 36505739, 2022). "CircFoxo3: In addition to its role in cancer cell apoptosis, circFoxo3 also controls cell proliferation by regulating G1-S phase transition by acting as a decoy for cyclin-dependent kinase 2 (CDK2) and the cell cycle inhibitor p21." (PMID 34449657, 2021). "Otherwise, CDK2-dependent cell cycle regulation is critical for proliferation, proliferation, growth, and maintenance of different cancer tumors." (PMID 33466812, 2021). "Owing to the exclusivity of cyclin E for CDK2 and its deregulation in some cancers, CDK2 is an attractive target in cancer therapy." (PMID 33803751, 2021).